TG (thyroglobulin)
Diseases named in the same sentence as TG in open-access papers (continued):
Sharing a sentence is not in itself a finding about the gene and the disease.
papillary thyroid carcinoma (continued). "Indeed, we confirmed the role of both miRNAs as diagnostic biomarkers for papillary thyroid cancer and their usefulness in monitoring cancer progression during patient follow-up, even when thyroglobulin levels are not informative." (PMID 39298113, 2025). "The mice expressing the human original HPV type 16 E7 protein under the control of the thyroglobulin promoter develop differentiated and functionally regulated thyroid goitres, before the occurrence of tumours mimicking human-differentiated follicular and papillary thyroid carcinomas." (PMID 18985036, 2008). "Conversely, papillary thyroid cancer (PTC) spheres had irregular shapes, downregulated expression of differentiation markers, and weak TSH-stimulated cAMP production and thyroglobulin expression." (PMID 36428988, 2022). "About 30% of patients with papillary thyroid cancer (PTC) experience persistent/recurrent disease within 10 years after an initial treatment, serum thyroglobulin (Tg) representing the gold standard for surveillance." (PMID 36428713, 2022). "Thyroglobulin and TPO are the main immunological target in HT and analogically also in the immune response in papillary carcinoma." (PMID 33991306, 2021). "Quantitative RT–PCR was performed (ADM3, HGD1, LGALS3, PLAB, TFF3, TG) in the needle wash-out of 156 FNAB of follicular adenoma (FA), adenomatous nodules, follicular and papillary thyroid cancers (TC) and normal thyroid tissues (NT)." (PMID 22223087, 2012). "Histology, however, revealed papillary carcinoma with focal solid mucin producing regions positive for CK19 and HBME and weakly positive for TTF1 and thyroglobulin." (PMID 19495405, 2009). "The clinical significance of thyroglobulin (Tg) expression in papillary thyroid cancer (PTC) has not been systematically explored in relation to the Ki-67 index, lymph node ratio (LNR), or other conventional prognostic predictors." (PMID 36658256, 2023). "The papillary carcinoma uses thyroglobulin as a tumor marker which is highly sensitive but not specific, CD56 was used in one-third of the cases of papillary cancers where its negativity was highly sensitive, as it was not applied in other variants so specificity could not be assessed." (PMID 35154933, 2022). "This makes unlikely to assume metastasis from the well differentiated papillary carcinoma, that stained positively for TTF1 and thyroglobulin and surgically removed nine years earlier." (PMID 28810922, 2017).
Obesity (89 papers, 2008 to 2025). Accumulation of substantial excess body fat. "According to a cross-sectional survey of 2505 individuals, obesity was significantly associated with anti-TG positivity after adjusting for sex, age, and smoking, but not with a higher anti-TPO positivity rate, which is consistent with our findings." (PMID 40806651, 2025). "Evaluating thyroglobulin antibodies is optional, as it has a low diagnostic value in the context of obesity." (PMID 38526760, 2024). "The evaluation of thyroglobulin antibodies, especially in the context of obesity, is currently considered a weak recommendation." (PMID 38201918, 2023). "Since current evidence is too weak to recommend testing of thyroglobulin antibodies (TgAb) in subjects with obesity, the ESE guideline suggests to consider it only in individual cases." (PMID 35781791, 2022). "The aim of this study was to investigate the role of thyroglobulin antibodies (TgAb) to define the thyroidal status in subjects with overweight or obesity." (PMID 35781791, 2022). "It is possible that obesity contributes to the generation of both anti-TPO and anti-TG autoantibodies, although experimental models have led to the hypothesis that the production of anti-TG may occur earlier, followed by the development of anti-TPO." (PMID 40806651, 2025).
Graves disease (88 papers, 2005 to 2025). Graves' disease is an autoimmune disorder that leads to overactivity of the thyroid gland (hyperthyroidism).It is caused by an abnormal immune system response that causes the thyroid gland to produce too much thyroid hormones. "Recurrent Graves' disease must be considered when there is an ongoing decrease in the levothyroxine dose requirement associated with a rise in the serum thyroglobulin level following near-total thyroidectomy." (PMID 38352081, 2024). "The disease-associated changes in miR-TG expression were further evaluated in SQ-PCR analysis of tissue samples taken from patients suffering from Graves’ Disease (GD), a disorder associated with high levels of thyroglobulin." (PMID 28855631, 2017). "The significance of thyroglobulin antibodies and thyroid peroxidase antibodies in Graves' disease remains equivocal." (PMID 38350897, 2024). "Her levothyroxine dose requirement gradually decreased and thyroglobulin level increased, which led to the diagnosis of recurrent Graves' disease." (PMID 38352081, 2024). "Thyroperoxidase (TPOAb) and thyroglobulin (TgAb) antibodies are highly prevalent in Graves’ disease (GD), but their significance is controversial." (PMID 37930957, 2023). "The overall contribution to the T3 secretion by D1 and D2 is reflected by the decrease in the T4/ T3 molar ratio from 15:1 in thyroglobulin-bound hormones to 11:1 in the thyroid output, which is observed in Graves’ disease and hyperfunctioning thyroid nodules." (PMID 36862025, 2023). "Serum thyroglobulin levels are often elevated in Graves’ disease (GD) and in most cases decrease during treatment." (PMID 33515213, 2021). "Titers of TgAb in autoimmune (Hashimoto’s) thyroiditis are usually higher than that of Graves’ disease, possibly due to the increase of circulating thyroglobulin concentration in Graves’ disease." (PMID 28804518, 2017). "We were the first to demonstrate the in vivo presentation of thyroglobulin (Tg) peptides by HLA-DR in thyroid glands affected by Graves’ disease." (PMID 24381570, 2013). "The principal autoantigens in Hashimoto's disease are thyroid peroxidase (TPO) and thyroglobulin (Tg), although these antibodies (anti-thyroid peroxidase (anti-TPO) antibody and anti-thyroglobulin (anti-Tg) antibody) are also found in 70% of Graves' disease patients." (PMID 35911325, 2022). "Positive rates of other thyroid autoantibodies, such as anti-thyroid peroxidase antibody (TPOAb) and anti-thyroglobulin antibody (TgAb), are also significantly increased in Graves' disease patients, which demonstrate that Graves' disease is an autoimmune thyroid disease from another point of view." (PMID 31885565, 2019). "Increased thyroglobulin antibodies were found in 31% of participants, with the highest PBDEs body burdens, in one study, and thyroglobulin antibodies are found in most of patients with Grave’s disease and chronic autoimmune thyroiditis." (PMID 25992849, 2015). "Findings indicative of Hashimoto’s or Graves diseases were evaluated in 792 patients by testing for anti-thyroid peroxidase antibody, anti-thyroglobulin antibody, free thyroxine (T4), thyroid stimulating hormone (TSH) and/or TSH receptor antibodies and/or thyroid sonography." (PMID 25800473, 2015). "However, as we mentiond before, Graves’ disease (GD) is an organ-specific autoimmune disorder characterized by the appearance of pathogenic autoantibodies against thyroid peroxidase (TPO), thyroglobulin (Tg), and the TSH receptor (TSHR)." (PMID 23189166, 2012). "Lending support to our results, a recent study found that men with ∑PBDEs > 95th percentile (193 ng/g lipids) had substantially increased odds of having detectable serum thyroglobulin antibodies (OR = 6.1; 95% CI, 1.9–19.2), which are found in 80% of Graves disease patients." (PMID 20562054, 2010).
Graves disease (continued). "IID: intrathyroid injection of dexamethasone; GD: Graves’ disease; TSH: thyroid-stimulating hormone; FT4: free thyroxin T4; TGAb: thyrotrophin receptor antibody; TPOAb: thyroid peroxidase antibody; TGAb: thyroglobulin antibody." (PMID 32555990, 2020). "Excluded were patients <18 years old, with sonographic features of HT but negative thyroid peroxidase (TPOAbs) or thyroglobulin autoantibodies (TgAbs), Graves’ disease, Down or Turner’s syndrome." (PMID 35528009, 2022). "The thyroid peroxidase antibody test and thyroglobulin antibody test used in that study are not specific for the diagnosis of Graves disease." (PMID 26962803, 2016). "Our finding of increased thyroglobulin antibodies in 31% of participants with the highest PBDE body burdens is potentially of biologic significance because thyroglobulin antibodies are found in 80–90% of patients with chronic autoimmune thyroiditis and 50–60% of patients with Grave’s disease." (PMID 19079713, 2008).
thyrotoxicosis (85 papers, 2005 to 2026). A hypermetabolic syndrome caused by the elevation of thyroid hormone levels in the serum. "The potential release of thyroglobulin, thyroid hormone stores, and cytokines can trigger a series of symptoms that can be associated with pain, tenderness, and symptoms of thyrotoxicosis." (PMID 26942022, 2016). "Blood tests performed 21 weeks (147 days) after the PVP-I gargling discontinuation showed TSH levels within the normal range (TSH, 0.94 μIU/mL; FT3, 3.4 pg/mL; FT4, 0.8 ng/dL; thyroglobulin, 28.6 ng/mL), indicating improvement in T3 thyrotoxicosis." (PMID 37653786, 2023). "Thyrotoxicosis of various origins leads to the release of peripheral thyroid hormones and thyroglobulin (TG), the main glycoprotein contained within the thyroid follicular lumen." (PMID 36969717, 2022). "His serum thyroglobulin was normal, arguing against thyroid hormone self-administration (thyrotoxicosis factitia)." (PMID 21722403, 2011). "The serum thyroxin and triiodothyronine ratio and a low thyroglobulin level can be considered in thyrotoxicosis of exogenous intake." (PMID 22152685, 2011). "According to previous observations, thyroglobulin is elevated in thyrotoxicosis." (PMID 33515213, 2021). "Exogenous IFN-α may also influence switching to a Th2 pathway, which can result in the development of autoantibodies (e.g., anti-TPO, anti-TG) resulting in thyrotoxicosis, due to thyroid follicular rupture and release of stored thyroid hormones into the circulation." (PMID 27042364, 2016). "TRAb, anti-TPO, and anti-thyroglobulin antibodies were negative, making the diagnosis of autoimmune thyroid diseases unlikely, so he was diagnosed with subacute thyrotoxicosis and started on propranolol 20 mg twice per day and slow tapering oral steroids (prednisolone)." (PMID 40656306, 2025).
diabetes (78 papers, 2011 to 2026). "In our cohort, thyroglobulin autoantibodies were measured at diabetes diagnosis, but since they proved less sensitive than TPO-Abs in our previous report, we did not analyze them during follow-up." (PMID 41255538, 2025). "This study investigated the relationship between thyroid autoantibodies—thyroglobulin antibodies (TgAb) and thyroid peroxidase antibodies (TPOAb)—and metabolic dysfunction-associated fatty liver disease (MAFLD) in patients with type 2 diabetes mellitus (T2DM)." (PMID 39703861, 2024). "There were differences in age, drinking, smoking, diabetes history, body mass index (BMI), thyroglobulin (TG), history of hypertension and hyperglycemia among the three groups (P=0.036, 0.018, 0.040, 0.029, 0.006, 0.034, 0.020, 0.010)." (PMID 31497547, 2019). "The potential role of comorbidities (diabetes, concurrent antihypertensive medication, treatment with l-thyroxine, and presence of antithyroid peroxidase/microsomes, anti-thyroglobulin, and/or anti-thyrotropin-receptor antibodies) was analysed." (PMID 29492700, 2018). "For instance, in patients with type 1 diabetes mellitus, glycosylated thyroglobulin might elicit THAb synthesis with high frequency." (PMID 28894436, 2017). "Distribution of the anti-TG and anti-TPO levels according to control, Type-I and Type-II diabetes." (PMID 40735558, 2025). "The non-stimulated thyroglobulin, LN dissection, number of LNs dissected, lymph node metastasis ratio, N stage, comorbidity of hypertension, comorbidity of diabetes, body mass index, and low-density lipoprotein were used to develop the models." (PMID 38589799, 2024). "Nonetheless, research including 179 children with diabetes found that 2.8% of the cohort had another AID at the time of the T1DM diagnosis, and 15.6% of the group tested positive for additional autoantibodies (anti-transglutaminase, anti-thyroglobulin, or anti-thyroid peroxidase antibodies)." (PMID 39845243, 2024). "The study assessed differences in the thyroglobulin antibody and thyroid peroxidase antibody between euthyroid Type-I and Type-II diabetes mellitus (DM) and control groups not using thyroid medication." (PMID 40735558, 2025).
goiter (54 papers, 2012 to 2026). Enlargement of the thyroid gland usually caused by lack of iodine in the diet, hyperthyroidism, or thyroid nodules. "The pathophysiology of the disease involves an autoimmune condition in which thyroid peroxide (anti-TPO) and thyroglobulin (anti-TG) autoantibodies cause lymphocytic infiltration of the thyroid gland, which often presents as goiter." (PMID 40506882, 2025). "In our cohort, several affected children exhibited elevated serum thyroglobulin and goiter in the setting of pathogenic SLC26A4 variants, findings consistent with the interplay between genetic susceptibility and chronic iodine deficiency." (PMID 40956475, 2025). "UIC is used to evaluate recent iodine intake, thyroglobulin shows thyroid activity whereas goiter rate reflects long term iodine deficiency." (PMID 35692388, 2022). "Lower iodide intake was also associated with higher thyroglobulin and prevalence of goiter, suggesting that the thyroid is overstimulated when iodide intake falls short of demand." (PMID 33466826, 2021). "Other genes that were also implicated in goiters include those encoding thyroglobulin, pendrin (PDS), thyroid oxidase 2, and RET." (PMID 24482635, 2014). "The clinical characteristics of patients with thyroglobulin gene mutations are diverse, and some patients are diagnosed by chance on examination of goiter in adults." (PMID 22934199, 2012). "The mild form of iodine deficiency may lead to goiter with unaltered levels of thyroid hormones and elevated levels of thyroglobulin (Tg)." (PMID 33620551, 2021). "However, high thyroglobulin levels and goiter may be also caused by iodine organification defects, which have been detected in nearly 20% of the patients with transient CH." (PMID 27086592, 2016). "Recently, mice with genetic deletion of thyroglobulin have been found to also exhibit net goiter growth but also substantial thyroid cell death despite the complete absence of thyroidal ER stress." (PMID 41979536, 2026). "The recommended biomarkers, based on the current evaluation system, include urine iodine concentration (UIC), thyroid-stimulating hormone (TSH), thyroglobulin (Tg), T4 and T3, and goiter." (PMID 36839326, 2023). "The biomarkers used to monitor iodine status are: urinary iodine concentration (UIC), thyroglobulin concentration in blood and goiter rate." (PMID 35692388, 2022). "It has been reported that the effects of smoking were pronounced in iodine-deficient areas, where smokers present a higher frequency of goiter and increased serum thyroglobulin levels." (PMID 35245310, 2022). "Several methods are recommended for the assessment of iodine nutrition in populations: urinary iodine concentration (UIC), thyroglobulin concentration in blood and goiter rate." (PMID 33989173, 2021). "The biallelic TG mutations identified in patient #2 have been reported previously and were consistent with the clinical presentation of goiter, low thyroglobulin levels, elevated iodide uptake, and normal perchlorate discharge test." (PMID 33692749, 2020). "We examined the effects of 26 weeks of iodine supplementation on thyroid hormones, thyroglobulin and goiter of lactating women and on T4, TSH and VIP in infants." (PMID 31589645, 2019). "Biomarkers of iodine status have focused on urinary iodine concentration and thyroid function, such as the presence of goiter or thyroid hormone measurements, including thyroid stimulating hormone, thyroxine, triiodothyronine, and thyroglobulin (Tg)." (PMID 28982133, 2017). "Then, we excluded those subjects with goiter or other abnormalities on physical examination, positive thyroid peroxidase antibodies (TPOAb), thyroglobulin antibodies (TGAb), and other laboratory abnormalities." (PMID 24365659, 2013). "Although structural information is available on recombinant and deglycosylated endogenous human thyroglobulin (hTG) from patients with goiters, the structure of native, fully glycosylated hTG remained unknown." (PMID 35013249, 2022).
goiter (continued). "We explored associations between iodide intake and urinary iodine concentration (UIC), urinary iodine/creatinine ratio (I/Cr), thyroid stimulating hormone, thyroglobulin, free triiodothyronine, free thyroxine and palpable goiter in a region of mild-to-moderate iodine insufficiency." (PMID 33466826, 2021). "Twenty-eight patients were excluded because of a goiter which, in itself, may affect serum thyroglobulin levels." (PMID 32182688, 2020). "Because H2O2 is the limiting factor for thyroglobulin iodination when the iodide supply is normal, DUOX2 mutations often cause thyroid dyshormonogenesis and are linked to CH associated with goiter or a thyroid gland of normal size in the presence of an iodide organification defect." (PMID 29650690, 2018). "High thyroglobulin levels and goiter in the TCH group may result from defects in iodine metabolism." (PMID 38546931, 2024). "Our case presented with goiter and tested positive for anti-TPO and TG, with ultrasound findings reporting a heterogeneous texture of the thyroid gland, multiple echogenic septae, and increased vascularity." (PMID 41024896, 2025). "Other methods recommended for the population iodine assessment are the goiter rate, serum thyroid-stimulating hormone (TSH), and serum thyroglobulin (Tg)." (PMID 35684009, 2022). "The iodine status of the population can be assessed by using four methods: urinary iodine (UI) concentration, the goiter rate, serum thyroid stimulating hormone (TSH), and serum thyroglobulin (Tg) levels." (PMID 31614658, 2019). "A 3-week old girl presented with a large goiter, serum TSH > 100 mIU/L (reference range: 0.7–5.9 mIU/L); free T4 < 3.2 pmol/L (reference range: 8.7–16 pmol/L); thyroglobulin (TG) 101 μg/L." (PMID 29720101, 2018). "Mutations in multiple genes have been shown to cause CH and are grouped into several categories depending on the presence or absence of goiter, level of serum thyroglobulin (TG), and other clinical characteristics." (PMID 29720101, 2018). "All six had the follicular type of thyroid carcinoma, a history of long-standing goiter as the first presentation of their disease, and an increased serum thyroglobulin compared to the nonhormone producing subjects." (PMID 25400957, 2014). "The two patients described here exhibited normal thyroglobulin levels that were inappropriately low for their very high TSH levels, and an absence of clinical goiter, although a moderately enlarged thyroid was observed in the female patient." (PMID 39015673, 2024). "Although clinically euthyroid with no goiter, maternal TSH was raised (60 mU/L) with normal TT4 (121 nmol/L, 9.40 μg/dL) and negative thyroid autoantibody (antithyroid peroxidase, thyroglobulin, TSH receptor) measurements." (PMID 37988295, 2024).